APOA5 (apolipoprotein A5)
Diseases named in the same sentence as APOA5 in open-access papers (continued):
Sharing a sentence is not in itself a finding about the gene and the disease.
cardiovascular disease (24 papers, 2008 to 2025). "APOA5 deficiency is associated with elevated plasma TG levels, which can increase the risk of cardiovascular diseases." (PMID 38521668, 2024). "The current study demonstrated the effect of the APOA5 rs662799 polymorphism on plasma TG levels and its strong association with the risk of cardiovascular disease in ESKD patients." (PMID 36071387, 2022). "Since the end-stage kidney disease patients are particularly prone to cardiovascular disease, we aimed to assess the potential association of the APOA5 -1113 T > C polymorphism with a risk of CVD in this group of patients." (PMID 36071387, 2022). "APOA5 CC homozygotes and TC heterozygotes have been associated with increased cardiovascular disease in various populations." (PMID 35387194, 2022). "The rs662799 polymorphism in the APOA5 gene has been reported to be associated with cardiovascular disease." (PMID 36071387, 2022). "The APOA5/4/C3/A1 gene cluster on chromosome 11q23 plays an important role in TG regulation; particularly variants occurring in the APOA5 gene have been extensively analyzed for their relationship with TG metabolism and cardiovascular diseases susceptibility." (PMID 32832146, 2020). "A significant correlation between the APOA5 gene polymorphism and the levels of plasma high-density lipoprotein-cholosteal and increased risk for cardiovascular disease was previously identified." (PMID 27152866, 2016). "In particular, an association between risk alleles for cardiovascular diseases and high cholesterol levels with differential promoter methylation of the apolipoprotein A-V (APOA5) illustrated the implication of meQTL in the biology of human diseases." (PMID 24822056, 2014). "In humans, a mutation in ApoA5, also called the Delhi gene, is linked to extremely elevated triglyceride levels and increased risk of cardiovascular disease." (PMID 25344410, 2014). "Numerous previous studies reported associations between common variants of APOA5 gene and differences in plasma TG levels, suggesting that they may be related to cardiovascular disease." (PMID 36071387, 2022). "These associations suggested that APOA5 gene is a functional candidate for cardiovascular disease." (PMID 36071387, 2022). "Moreover, further studies with larger sample sizes are needed to verify the mechanism and associations of the APOA5 c.553G>T polymorphism with apoA5 concentrations and cardiovascular disease risk factors." (PMID 29211729, 2017). "Apolipoproteins have been demonstrated to play physiological roles on nutrition transport and energy metabolism, and numerous variants have been revealed in some apolipoproteins including ApoA1, ApoA5, ApoB, ApoC3 and ApoE, which are associated with the risk of cardiovascular disease." (PMID 21799896, 2011). "Over the past decades, genetic variability in the APOA5/A4/C3/A1 cluster has been associated (to varying extents) with variability in plasma lipid, apolipoprotein and lipoprotein levels and with an increased risk of cardiovascular disease." (PMID 18789138, 2008). "Furthermore, new studies are continuously being performed to identify whether APOA5 polymorphisms are associated with cardiovascular diseases occurrence." (PMID 32832146, 2020). "Therefore, we believe that the identification of carriers of the minor allele of the APOA5 −1131T>C polymorphism may prove helpful in predicting MS susceptibility and overall risk assessment for metabolic diseases such as cardiovascular disease." (PMID 23509746, 2013). "For this reason, APOA5 plays a pivotal role in regulating plasma TAG, a risk factor for cardiovascular disease." (PMID 35387194, 2022). "These regions contain genes associated with calcium channels (CACNA1S), renin catalysis (REN), blood groups (ABO), apolipoprotein (APOA5), and cardiovascular diseases (RASGRP1)." (PMID 25519368, 2014).
tumor (7 papers, 2020 to 2025). "Increased APOA5 expression was associated with PIK3CA mutation in tumor specimens and poor response to first-line chemotherapy, which was an independent detrimental factor for chemotherapy sensitivity in CRC patients." (PMID 38848145, 2024). "Mechanistically, our discovery analysis indicated that expressions of APOA1, APOC3, and APOA5 are inversely associated with tumor-infiltrating immune cells, and we proposed that they exert an immunomodulatory effect on the tumor microenvironment." (PMID 34226567, 2021). "Notably, studies have demonstrated a higher prevalence of APOA5 copy number loss in intraductal tumors among East Asian women under the age of 50, suggesting its diverse involvement in tumor biology through immunomodulation within the tumor microenvironment." (PMID 38300336, 2024). "Studies on PIK3CA mutations and tumor lipid metabolism reveal that the PIK3CA-E545K mutation promotes nuclear accumulation of SREBP1, enhancing transcription of apolipoprotein A5 (APOA5) and thereby mediating platinum-based drug resistance in CRC." (PMID 40718481, 2025). "Tumor sphere number was assessed and quantified after 7 days of culture, which showed an increase in tumor sphere number and volume in APOA5 overexpressing cells compared with control cells." (PMID 38848145, 2024). "In a study of East Asian breast patients, researchers found that lower expressions of APOA5 and APOC3 were associated with higher ESTIMATE immune scores, which means a large number of tumor-infiltrating immune cells." (PMID 35692496, 2022). "Lower APOA1, APOC3, and APOA5 expressions were associated with higher ESTIMATE immune scores, indicating an abundance of tumor-infiltrating immune cells." (PMID 34226567, 2021). "The tumor samples of the TCGA displayed undetectable levels of APOA5 and PON1, as these proteins are found at the systemic level." (PMID 34439311, 2021). "The lower levels of APOA1, APOC3, and APOA5 expression were associated with higher ESTIMATE immune scores, which indicated an abundance of tumor-infiltrating immune cells." (PMID 34226567, 2021). "Down-regulated genes contain markers enriched in mature hepatocytes (Tat, Cyp7a1, Apoa5, Pck1, Cyp3a11, Mup3 or Acsl1) and tumor suppressors (Lect2, Wfdc17 or Efemp1)." (PMID 32372053, 2020). "Notably, the xenografts from HCT116/APOA5 cells showed an increase in tumor growth compared with parental cells." (PMID 38848145, 2024). "The results demonstrated APOA5 positive expression in the cytoplasm of tumor cells." (PMID 38848145, 2024).
heart disease (1 paper, 2008). "The 11q23-24 human genome location is well known for a cluster of genes (APOA1, APOC3, APOA4, and APOA5), which effect the lipid levels as well as is associated with DM and heart disease." (PMID 19038053, 2008).
APOA5 also shares sentences with these, for which no sentence is quoted: metabolic disease (6 papers); pancreatitis (6); hypothyroidism (4); cancer (3); hyperlipoproteinemia (3); acute coronary syndrome (2); familial chylomicronemia (2); hyperlipoproteinemia type V (2); steatosis (2); acute kidney injury (1); acute-on-chronic liver failure (1); antibody deficiency against (1); arteriosclerosis (1); asthma (1); autoimmune conditions (1); autosomal recessive disease (1); cerebral infarction (1); cholesterol ester storage disease (1); chronic renal failure (1); colitis (1); dilated cardiomyopathy (1); dyslipidaemia (1); endothelial dysfunction (1); gout (1); heart failure (1); hyperlipoproteinemia type 1D (1); hyperlipoproteinemia type 3 (1); Impaired glucose tolerance (1); infection (1); inflammatory bowel disease (1).
A further 15 diseases each share a sentence with APOA5 in 1 paper.